MTOR (mechanistic target of rapamycin kinase)
Diseases named in the same sentence as MTOR in open-access papers (continued):
Sharing a sentence is not in itself a finding about the gene and the disease.
tumor (continued). "However, CRCC is a highly vascular tumor, and in the last 20 years, tyrosine kinase inhibitors (TKI) and anti-angiogenic agents targeting the VEGF pathway have been found to benefit patients with CCRCC, including targeted rapamycin inhibitors (MTOR) as well." (PMID 37305384, 2023). "In addition, astrocytes express microRNA targeting PTEN, which is transported to tumor cells through exosomes to inhibit the expression of PTEN, thereby activating PI3K/AKT/mTOR pathway, increasing the secretion of CCL2, recruiting myeloid cells, reducing cell apoptosis, and promoting tumor growth." (PMID 37228619, 2023). "In summary, it was revealed that the LINC00511–hsa-miR-625–5p-SEMA6A axis could regulate tumor autophagy, drug resistance, and apoptosis through phagosome, ABC transporters, and mTOR signaling pathways in SKCM, making it as a promising therapeutic target and a prognostic biomarker." (PMID 37434634, 2023). "Given that imipridones inhibit cell proliferation and tumor growth through effects on the AKT/mTOR pathway in EC36, we next investigated whether the AKT/mTOR pathway was involved in the synergistic anti-proliferative effects of olaparib and ONC206 in the EC cell lines." (PMID 37069726, 2023). "Also, curcumin affects of cell cycle-related genes and inhibits tumor proliferation by controlling a number of miRNAs, which lower proteasome activity, prevents phosphorylation of JAK1, STAT1, and STAT3 proteins, and blocks mTOR and Notch1 pathways." (PMID 38154206, 2023). "However, the proportion of available matched negative controls does not show statistically significant differences between the p-mTOR-positive and p-mTOR-negative tumor core groups." (PMID 37623437, 2023). "Moreover, a combination of mTOR and CDK4/6 inhibitors may prevent pathway reactivation downstream of PI3K, interfering with the survival of resistant cells and consequent tumor escape." (PMID 36792625, 2023). "Thirdly, mechanistically, we focused on the effect of CENP-N on AKT/mTOR signaling pathway, which, although important, may not be the only pathway regulating tumor radiosensitivity." (PMID 37940975, 2023). "Jiang and colleagues compared the effects of PA (low-intensity, consistent, self-determined wheel running that mimicked the national recommendation of 10,000 steps), restricted energy intake, and no PA on tumor incidence and mTOR pathway activation in tumors using a well-designed mouse model." (PMID 36895729, 2023). "Interestingly, in addition to its more lethal effect on tumor cells than other PI3K-Akt-mTOR pathway inhibitors, paxalisib was non-toxic to normal skin cells, including keratinocytes and fibroblasts." (PMID 37046703, 2023). "In addition, the combination of buparlisib and a MEK inhibitor trametinib has a synergistic anti-tumor effect, confirming that crosstalk between PI3K/AKT/mTOR and MAPK/MEK/ERK signaling may contribute to PI3K inhibitor resistance." (PMID 35806358, 2022). "However, BR CRC cells showed an increase in autophagy mediated by the activation of Akt/mTOR signaling pathway compared to their respective PT CRC cells, suggesting that autophagy in BR CRC cells appears to be tumor-protective and therefore, supports BR CRC cell survival." (PMID 36359211, 2022). "Therefore, it is conceivable that targeting Wnt/β-catenin alone, either directly or indirectly (such as with mTOR inhibitors), is not sufficient to induce tumor regression." (PMID 35166233, 2022). "In addition, hypoxic but not normoxic tumor exosomes enhance oxidative phosphorylation in BMDMs via the transfer of let-7a miRNA, suppressing the insulin-Akt-mTOR signaling pathway." (PMID 36224346, 2022).
tumor (continued). "In this context, we studied the previously unexplored senostatic efficacy of the dual mTOR complex inhibitor, INK-128, demonstrating for the first time that INK-128 effectively prevents radiation-induced senescence and radiation-enhanced tumor colonization and growth in vivo." (PMID 35158337, 2022). "Finally, we estimated the role of each gene in tumor-related pathways using the GSVA algorithm, including apoptosis, DNA damage response, cell cycle, hormone AR, hormone ER, PI3K/AKT, EMT, RAS/MAPK, RTK, and TSC/mTOR." (PMID 35309940, 2022). "Among the numerous targets of Notch are proteins that play a key role in tumor development and progression, such as the hairy and enhance of split (HES) family, hairy/enhancer of spit related with YRPW motif (HEY), nuclear factor-kappa B (NF-κB), VEGF, mTOR, cyclin D1, c-myc, p21, p27, and Akt." (PMID 35684449, 2022). "Proof-of-principle efficacy for the combination of the dual AKT/mTOR inhibitor NVP-BEZ235 (dactolisib) with trabectedin was obtained in vitro and in vivo using CDS PDX-derived cell lines, demonstrating a strong inhibition of local tumor growth and multiorgan metastasis." (PMID 34903601, 2022). "This trial did not demonstrate a clinically significant anti-tumor effect, which led the authors to hypothesize that the beneficial effect of metformin is in its synergistic activity with everolimus to inhibit mTOR." (PMID 36422290, 2022). "PI3K/AKT/mTOR and the other signaling pathways induce the expression of EMT-promoting transcription factors (TF) (e.g., zinc finger E-box binding homeobox 1 (ZEB1), SNAIL, TWIST), which are responsible for the eventual acquisition of mesenchymal traits by tumor cells." (PMID 35326492, 2022). "Additionally, the anti-angiogenic effect of quercetin has been closely linked to the decrease of VEGF-A, MMP2, and MMP9 expression, as well as to the inhibition of both tumor growth and angiogenesis by targeting VEGFR2 regulated by AKT/mTOR/P70S6K signaling pathway." (PMID 35204240, 2022). "First, we used unsupervised clustering methods to classify 375 tumour samples from The Cancer Genome Atlas (TCGA) database into three molecular subgroups (Cluster A, Cluster B, and Cluster C) based on the three characteristic pathways of GFRs: KRAS, AKT, and MTOR." (PMID 36387125, 2022). "Similarly, pathway enrichment results revealed a marked involvement in the JAK–STAT, interferon, and mTOR signaling pathways, suggesting that MTAP/CDKN2AMUT may activate the anti-tumor immune response in the TME of RCC." (PMID 35979371, 2022). "Moreover, several essential pathways, such as epidermal growth factor receptor (EGFR), phosphatidylinositol 3-kinase (PI3K)/protein kinase B (PKB, Akt)/mammalian target of rapamycin (mTOR), and Ras, can regulate SREBP-1 activation to mediate tumor growth and metastasis." (PMID 35912181, 2022). "To explore the signaling pathways involved in the PD-L1-mediated enhancement of tumor cell proliferation, migration, and invasion, we analyzed the influence of PD-L1 overexpression on tumorigenic pathways, including mitogen-activated protein kinase (MAPK), Akt/mTOR, and Wnt/β-catenin pathways." (PMID 36232331, 2022). "In conclusion, it could be stated that LAGE3 has prognostic prediction value and may influence HCC tumor progression by promoting the proliferation, survival, migration, invasion, and anti-apoptotic ability of HCC cells through PI3K/AKT/mTOR and Ras/RAF/MAPK pathways." (PMID 35313850, 2022). "Depending on context, EV and plasma miRNAs may act directly or via tumor-interacting immune components to modulate mTOR/AKT total protein levels or activity state (i.e., by downregulating upstream regulators of mTOR/AKT), thereby influencing tumor cell behavior." (PMID 35461372, 2022).
tumor (continued). "Furthermore, in the case of acquired resistance, palbociclib is unable to inhibit the Rb signal, and thus loses control of tumor cell growth, while targeted PI3K therapy can block PI3K/AKT/mTOR pathway, thus effectively inhibiting the proliferation of resistant cells." (PMID 38089455, 2022). "Since PI3K/AKT/mTOR is only one of numerous pathways activated in UM, the simultaneous blocking of several signaling routes, for instance MAPK and AKT, might be essential for apoptosis induction and the control of tumor growth." (PMID 35804957, 2022). "Since SFN modulated AKT/mTOR signaling and acted on CDKs and cyclins, suppression of the AKT/mTOR pathway and alterations of the CDK–cyclin axis may contribute to SFN’s effects on tumor growth and proliferation." (PMID 36230603, 2022). "This is, for example, what could be envisaged for patient MA01, whose tumor organoid was particularly sensitive to the mTOR inhibitor, everolimus, as well as to crizotinib, foretinib, and dasatinib, drugs that do not target mTOR." (PMID 35743016, 2022). "Similarly, LINC01554 is a novel tumor suppressor and downregulated by miR-365a in hepatocellular carcinoma cells, enabling cancer cells to achieve higher aerobic glycolysis by regulating PKM2 and Akt/mTOR signaling pathways to maintain cell growth advantage." (PMID 36124026, 2022). "In up to 24 tumor types, Tet has been shown to have a significant effect through Wnt/β-catenin signaling pathway, MAPK signaling pathway, Reactive oxygen species signaling pathway, PI3K/Akt/mTOR signaling pathway and NF-κB signaling pathway mediating its role in tumors." (PMID 36052124, 2022). "In a multivariate analysis including including pT, pN, tumor grade, tumor localization and p-mTOR expression, p-mTOR could not be confirmed to be a biomarker for prognosis (p = 0.8879)." (PMID 35201501, 2022). "In addition, it is suggested that in HCC tumors, the elevated BCAA levels promote hyperactivation of mTOR signaling for tumor growth rather than being oxidized for energy demands." (PMID 35409380, 2022). "Neurofibromin works as a tumor suppressor by reducing RAS-GTP mediated activation of its effector pathways, including MAPK and phosphoinositide 3-kinase (PI3K), and thus regulates cell growth and proliferation though downstream proteins (e.g., RAS, BRAF, mTOR)." (PMID 35599811, 2022). "Tumor intrinsic pathways that correlated with ICR score in these tumors are TNFR1, PI3K Akt mTOR signaling, Immunogenic cell death, Apoptosis, mTOR and others, while signatures inversely correlated with survival in both tumors include barrier genes, mismatch repair, proliferation, G2M checkpoints." (PMID 35690832, 2022). "More importantly, exogenously added PTEN-Long to HepG2 cells resulted in reduced p-AKT, p-PRAS40, and p-mTOR, which inhibited tumor cell proliferation and migration without any significant change induced in HepG2 cells after treatment with exogenous PTEN protein." (PMID 35647006, 2022). "For example, ATM regulates radiation-induced autophagy through the mTOR pathway, MAPK14 pathway, JNK pathway, and PI3KIII pathway, and complete lack of ATM function results in the failure of autophagy induction in tumor cells or switches the cell stress response to senescence." (PMID 35888608, 2022). "In addition, we queried the phosphorylation status of the proteins and found that mTOR and MAP2K1 showed consistent increases (p<0.05) in dephosphorylation, while EGFR was consistently hyper-phosphorylated (p<0.05) in higher tumor grades (normal, grades I~III)." (PMID 35655775, 2022).
tumor (continued). "One possibility to explain how glycolysis can induce autophagy alone, or a mixed mesenchymal/autophagic phenotype in tumor cells, is to assume that the negative control exerted by mTOR on AMPK and ULK1, or on components of the autophagy pathway itself, becomes disabled." (PMID 35326492, 2022). "Inhibition of mTOR kinase activity by temsirolimus limits not only the division of neoplastic cells but also lowers the level of HIF and VEGF proteins in the tumor or its environment, which inhibits the development of tumor vascularization (antiangiogenic effect)." (PMID 36232388, 2022). "Given the aberrant activation of the PI3K/AKT/mTOR pro-survival pathway observed in DDLPS, idasanutlin was tested in combination with the PI3K/mTOR inhibitor NVP-BEZ235 resulting in enhanced cell growth inhibition, apoptotic cell death, and reduction of tumor growth rate." (PMID 36119484, 2022). "Phosphorylation of PI3K, AKT, and mTOR decreased in the separately treated PAG, L-Asp, and AOAA groups compared to control, which may lead to both decreased cellular proliferation and increased cell death and suppress tumor growth." (PMID 35807290, 2022). "In addition, CTSK can promote tumor cells proliferation, invasion and migration, and its mechanism may be related to RANK/RANKL, TGF-β, mTOR and the Wnt/β-catenin signaling pathway." (PMID 36005209, 2022). "Since clinical trials targeting the mTOR pathway in GBM have not shown the expected results so far, it is of great interest that microglia rather than tumour cells might be used as the primary target of mTOR inhibition in GBM." (PMID 36555253, 2022). "In addition, it was demonstrated that a high miR-21 expression in HCC represses the expression of phosphatase and tensin homolog (PTEN) tumor suppressor and increases the activity of AKT and mammalian target of rapamycin (mTOR) kinase pathways, which promotes cell proliferation and survival." (PMID 35327559, 2022). "Furthermore, decreased phosphorylation of mammalian target of rapamycin (mTOR), S6 ribosomal protein and eukaryotic initiation factor 4E binding protein-1 (4E-BP1) occur in the ApcMin/+ mouse tumor model and they are responsible for the suppression of protein synthesis." (PMID 35441960, 2022). "In addition, tumor growth was reduced by combined treatment with AKT and mTOR inhibitors in an orthotopic xenograft mouse model of an EpCAM+ HCC cell line (Huh7) and primary patient-derived EpCAM+ HCC cells (HCC1) as well as a CD90+ HCC-related cell line (SK-HEP1) in vivo." (PMID 35454789, 2022). "For example, PDL1 expressed in tumor cells functionally regulates cell proliferation and survival through the ERK/mTOR pathway, EMT induction through the RAS/ERK pathway, and cell metabolism through the Akt/mTOR pathway in addition to the immune brake in the PD1-expressing cells." (PMID 36211375, 2022). "Therefore, simultaneous targeting of PI3K/mTOR and AR signalling may be of clinical value for LAR tumours." (PMID 36077812, 2022). "MDSC-related miRNA could also modulate the activity of other signaling pathways, stimulating mechanistic target of rapamycin (mTOR) and protein kinase B (Akt) triggering phosphatase and tensin homolog deleted on chromosome 10 (PTEN), leading to the accumulation of tumor- derived MDSCs." (PMID 36439186, 2022). "Taken together, C2orf40, as a tumor suppressor gene, could inhibit the migration ability of NPC cells and enhance the sensitivity of NPC cells to chemotherapy and radiotherapy through inhibiting HRR and the PI3K/Akt/mTOR signaling pathway." (PMID 35676661, 2022). "Although autophagy can be involved in both tumor suppression and tumor promotion, it has been proposed that the downregulation of PFKFB4 (or the inhibition of its kinase activity) can help inhibit the SRC3/Akt/mTOR pathway, and hence direct autophagy to promote apoptosis of tumor cells." (PMID 35056904, 2021).
tumor (continued). "Besides, we preliminarily investigated the potential mechanism of ENO1-mediated tumor growth, that ENO1 might promote the biological properties of LCSCs by AMPK/mTOR pathway." (PMID 33579362, 2021). "Inhibition of JAK/STAT3 or PI3k/AKT/mTOR pathways, which have shown potential therapeutic implications in DLBCL, may also ultimately impact PD-L1 expression in the tumour cells, providing additional rationale for future clinical evaluation with PD-1/PD-L1 blockade combinations." (PMID 34572910, 2021). "Interestingly, datasets generated from our negative and positive selections uncovered an oncogenic (mTOR) and a tumor suppressor (Hippo) signaling pathways as the main regulators of the tumorigenic process in TNBC." (PMID 34031411, 2021). "Finally, a combination of an AURKA inhibitor, MLN8237 (alisertib) with NVP-BEZ235 in a 786-0 VHL-null mouse xenograft model of RCC dramatically reduced tumor burden, highlighting the potential for co-inhibition of AKT, mTOR and AURKA as a clinical intervention strategy." (PMID 34002003, 2021). "Furthermore, a novel dual PI3K/mTOR inhibitor, VDC-597, showed dose-dependent inhibition of both Akt1 and 4eBP1, reduction of proliferation, migration and VEGF production, and promotion of tumor cell apoptosis in three canine HSA cell lines." (PMID 34296746, 2021). "Moreover, knocking down PRMT5 could weaken the tumor growth and lung metastasis in vivo while upregulating the LKB1 expression and the p-AMPK level and downregulating the p-mTOR expression." (PMID 34124017, 2021). "Currently, there are FDA-approved inhibitors against mTOR pathway for other purposes, it is necessary to explore their efficacy to reverse anti-EGFR resistance in these tumours and looking for markers to elucidate which patients could benefit from this strategy." (PMID 34359657, 2021). "EGFR signal activated PI3K/AKT/mTOR pathway, and up-regulated HIF-1α-mediated enhancement of glucose uptake and glycolysis-related gene expression, which may be driven by or in synergy with c-MYC to promote tumor proliferation." (PMID 35071325, 2021). "Moreover, knocking down PRMT5 could weaken the tumor growth and lung metastasis in vivo with upregulating the LKB1 expression and the p-AMPK level and downregulating the p-mTOR expression." (PMID 34124017, 2021). "In addition to miRNAs, noncoding RNAs, such as long non-coding RNAs (lncRNAs) and circular RNAs (circRNAs), have also attracted extensive attention due to their important regulatory roles in tumor development involving in Wnt/β-catenin, PI3K/AKT/mTOR, Notch and NF-KB pathways." (PMID 34135756, 2021). "The following experiments were performed to evaluate the effects of simultaneous targeting of DNA-PK, PI3K and mTOR with PI-103 on the radiation sensitivity, marker protein expression, DNA damage/repair, the degree of apoptosis, autophagy, and cell cycle alterations in two GBM tumor cell lines." (PMID 34763650, 2021). "Additionally, PI3K/Akt/mTOR signaling, downstream pathway of hsa_circ_0000199-miR-206/miR-613 axis in TNBC, was reported to stimulate tumor onset and to potentiate metastasis and proliferation of tumor (e.g. TNBC) cells." (PMID 33495420, 2021). "mTOR exerts an influence in the interaction of many kinds of cells and in many links, such as regulating the function of CD8+ T, thereby promoting the immune killing effect of T cells on tumor cells, and inhibiting the activation of NK cells, and finally playing an immunosuppressive effect." (PMID 33546704, 2021).